SLC19A1 (solute carrier family 19 member 1)
Description:
Antiporter that mediates the import of reduced folates or a subset of cyclic dinucleotides, driven by the export of organic anions. Acts as an importer of immunoreactive cyclic dinucleotides, such as cyclic GMP-AMP (2'-3'-cGAMP), an immune messenger produced in response to DNA virus in the cytosol, and its linkage isomer 3'-3'-cGAMP, thus playing a role in triggering larger immune responses. Mechanistically, acts as a secondary active transporter, which exports intracellular organic anions down their concentration gradients to facilitate the uptake of its substrates. Has high affinity for N5-methyltetrahydrofolate, the predominant circulating form of folate. Also mediates the import of antifolate drug methotrexate. 5-amino-4-imidazolecarboxamide riboside (AICAR), when phosphorylated to AICAR monophosphate, can serve as an organic anion for antiporter activity.
Synonyms: FOLT; IFC-1; RFC; hRFC; RFT-1; hSLC19A1; RFC1; CHMD; IFC1; IMD114; MEGAF; REFC
Tractability: Small molecule: a structure with a bound ligand is known; a high-quality ligand is known. Antibody: UniProt places it where antibodies can reach, with high confidence; its Gene Ontology location is reachable by antibodies, with high confidence; UniProt predicts a signal peptide or a membrane-spanning region; the Human Protein Atlas places it where antibodies can reach. PROTAC: ubiquitination databases record sites on it; a small molecule that binds it is known.
Target class: SLC19 family of vitamin transporters; Transporter; Electrochemical transporter; SLC superfamily of solute carriers
Chemical probes: PD081666, PRALATREXATE, RALTITREXED
Safety:
Unwanted effects reported when the protein is acted on. In parentheses: how it was acted on, where the effect was seen, and who reports it.
adverse events (source: ClinPGx)
drug toxicity (source: ClinPGx)
Gene: Protein-coding gene on chromosome 21 (45,493,572 to 45,573,564, reverse strand). Ensembl gene ENSG00000173638.
Subcellular location: Cell membrane; Apical cell membrane; Basolateral cell membrane
Subcellular location (Human Protein Atlas): Plasma membrane
Pathways (Reactome):
Metabolism: Metabolism of folate and pterines
Gene Ontology:
Molecular function: 2',3'-cyclic GMP-AMP binding; antiporter activity; cyclic-GMP-AMP transmembrane transporter activity; folate:monoatomic anion antiporter activity; folic acid transmembrane transporter activity; methotrexate transmembrane transporter activity; folic acid binding; transmembrane transporter activity; xenobiotic transmembrane transporter activity; vitamin transmembrane transporter activity
Biological process: cyclic-GMP-AMP transmembrane import across plasma membrane; folate import across plasma membrane; folate transmembrane transport; folic acid transport; methotrexate transport; positive regulation of cGAS/STING signaling pathway; folic acid metabolic process; transmembrane transport; transport across blood-brain barrier; xenobiotic transmembrane transport; female pregnancy; monoatomic anion transmembrane transport; response to toxic substance; response to xenobiotic stimulus; vitamin transport
Cellular component: apical plasma membrane; basolateral plasma membrane; plasma membrane; brush border membrane; membrane
Genetic constraint (gnomAD): Loss-of-function variants: 38 observed, 31.4 expected, observed/expected ratio (o/e) 1.21, 90% interval 0.93 to 1.59. The synonymous counts are far from expectation, so gnomAD's model fits this gene poorly and the ratio says little. Missense variants: 831 observed, 777.54 expected, observed/expected ratio (o/e) 1.07, 90% interval 1.01 to 1.13. Synonymous variants: 460 observed, 371.41 expected, observed/expected ratio (o/e) 1.24, 90% interval 1.15 to 1.34.
Gene-disease validity (ClinGen):
ClinGen rates the evidence that SLC19A1 causes each of these diseases.
immunodeficiency 114, folate-responsive (autosomal recessive): Limited.
Homologues: Orthologues: chimpanzee SLC19A1 (99% identical), macaque SLC19A1 (91% identical), rabbit SLC19A1 (63% identical), dog SLC19A1 (61% identical), guinea pig SLC19A1 (58% identical), mouse Slc19a1 (58% identical), rat Slc19a1 (57% identical), tropical clawed frog slc19a1 (49% identical), zebrafish slc19a1 (47% identical), Drosophila melanogaster CG17036 (24% identical), Drosophila melanogaster CG6574 (24% identical), Caenorhabditis elegans folt-1 (24% identical), and 3 more. Paralogues in human: SLC19A3 (32% identical), SLC19A2 (31% identical).
Diseases named in the same sentence as SLC19A1 in open-access papers:
SLC19A1 is named in the same sentence as 67 diseases in open-access papers, as found by Europe PMC text mining. Sharing a sentence is not in itself a finding about the gene and the disease. The quoted sentences say what the papers report.
osteosarcoma (8 papers, 2017 to 2025). A usually aggressive malignant bone-forming mesenchymal neoplasm, predominantly affecting adolescents and young adults. "SLC19A1 or Solute Carrier family member protein is a gene implicated in placental carcinomas and pediatrics osteosarcomas." (PMID 32894086, 2020). "Polymorphisms in SLC19A1 have been associated with response to methotrexate treatment in pediatric osteosarcoma." (PMID 30991985, 2019). "Although the mechanism behind this has not been well elucidated, one study determined the prognostic value of SLC19A1 in osteosarcoma, which is consistent with the findings above." (PMID 40149548, 2025). "Although studies have reported its association with osteosarcoma and leukemia resistance to chemotherapies, the possible mechanisms of SLC19A1 in most of the other tumors have not yet been elucidated." (PMID 40149548, 2025). "In addition, the sequence alterations of the entire coding region of the SLC19A1 gene were studied in 162 patients with different types of osteosarcoma." (PMID 38074116, 2023). "SLC19A1 was significantly highly expressed in osteosarcoma cells." (PMID 35958555, 2022).
colorectal cancer (6 papers, 2011 to 2025). A primary or metastatic malignant neoplasm that affects the colon or rectum. "In stage III colorectal cancer, high expression of SLC19A1 and SLC46A1 correlated with improved disease-free survival in patients receiving 5-FU/leucovorin." (PMID 41376620, 2025). "The involvement of ZC3H12C in colorectal cancer has been previously reported, whereas the role of SLC19A1 remains unexplored." (PMID 41376620, 2025). "Functional validation experiments demonstrated that knockdown of SLC19A1 significantly inhibited cell proliferation, suggesting that SLC19A1 may act as a potential oncogene in the pathogenesis of colorectal cancer." (PMID 41376620, 2025). "To investigate its potential involvement in colorectal cancer cell proliferation, we transfected HCT116 and SW480 cell lines with shRNA targeting SLC19A1." (PMID 41376620, 2025). "While, to our knowledge, SLC19A1 rs1051266 has not been evaluated for childhood ALL risk, it has been associated with colorectal cancer and prostate cancer." (PMID 24367687, 2013).
acute lymphoblastic leukemia (5 papers, 2015 to 2024). Leukemia with an acute onset, characterized by the presence of lymphoblasts in the bone marrow and the peripheral blood. "In acute lymphoblastic leukemia, miR-595 downregulates the methotrexate transporter SLC19A1 with rs1051296 G > T polymorphism, and this decrease in SLC19A1 causes reduced methotrexate influx and sensitivity." (PMID 35755805, 2022). "For example, increased intracellular transport of methotrexate via SLC19A1 and higher cellular methotrexate polyglutamates have been documented in hyperdiploid acute lymphoblastic leukemia cells with extra copies of chromosome 21." (PMID 32660497, 2020).
mucositis (5 papers, 2020 to 2025). Mucositis is inflammation and damage of the mucous membranes lining the mouth and other parts of the gastrointestinal (GI) tract. "The presence of rs1051266 (SLC19A1) variant in homozygosis is related to greater severity in mucositis, whereas its absence is associated with a higher probability of toxic liver disease, neutropenia, pancreatitis, vomiting, and myelosuppression." (PMID 41301675, 2025). "In their study, the rs2838958 SLC19A1 polymorphism was found to be associated with mucositis that was developed after chemotherapy." (PMID 39451565, 2024). "Preliminary evidence showed that SLC19A1 polymorphism (SLC19A1 80G>A), an influx transporter involved in MTX uptake in gut and liver cells, may have a protective effect on the occurrence of mucositis." (PMID 32848787, 2020).
prostate carcinoma (5 papers, 2013 to 2026). A carcinoma that arises from epithelial cells of the prostate gland. "Upregulated SLC19A1 thus encode a membrane protein to transport folate, which decreases ROS levels and promotes prostate cancer proliferation." (PMID 35006436, 2020). "High expression of circ_SLC19A1 significantly promoted the growth and invasion of prostate cancer cells." (PMID 35592755, 2022). "In addition, the circular RNA formation of SLC19A1 was identified to promote the prostate cancer progression via extracellular vesicles." (PMID 40149548, 2025). "Circ_0062019 and its host gene SLC19A1 were significantly upregulated in prostate cancer." (PMID 35006436, 2020). "Circ_SLC19A1 can sponge miR‐497 to increase the level of oncogene SEPT2, thus inducing the ERK1/2 pathway and modulating the growth and invasion of prostate cancer cells." (PMID 35592755, 2022).
rheumatoid arthritis (5 papers, 2014 to 2025). A chronic, systemic autoimmune disorder characterized by inflammation in the synovial membranes and articular surfaces. "MTHFR 677T may be used to help identify patients with an increased likelihood of methotrexate-related adverse events; SLC19A1 A80G has been associated with decreased methotrexate therapeutic response in individuals with rheumatoid arthritis." (PMID 25106483, 2014). "Previous pharmacogenetic studies in psoriasis and rheumatoid arthritis have reported associations between MTX response and polymorphisms in SLC19A1, MTHFR, and ABC transporters, although the results have been inconsistent." (PMID 41590498, 2025). "Two variants in ATIC (rs4673993, T allele) and SLC19A1 (rs1051266, C allele), which impact methotrexate (MTX) efficacy in rheumatoid arthritis, demonstrated high prevalence among the enrolled Saudis with allele frequencies of 71% and 48%, respectively." (PMID 40376268, 2025). "Methotrexate and sulfasalazine have served as classic SLC19A1 inhibitors and are commonly used to treat rheumatoid arthritis and inflammatory bowel disease." (PMID 40149548, 2025).
breast carcinoma (4 papers, 2011 to 2022). "Our study indicated that high expression of SLC19A1 was related to poorer survival in breast cancer, and therefore, the effects and potential functions of SLC19A1 on breast cancer initiation and progression warrant further investigation." (PMID 35574387, 2022). "In breast cancer, the strongest associations included either SNPs in or gene burden scores for genes LDLRAD1, SLC19A1, FGFBP3, CASP5, MMAB, SLC16A6, and INS-IGF2." (PMID 23555315, 2013). "And for the survival analyses of OS, high expressions of SLC19A1, CYC1, RRM2B, and OCRL and downregulation of RPS14 were significantly related to more unfavorable OS in breast cancer, which further confirmed the validity of selected genes." (PMID 35574387, 2022). "From the results, we found that mRNA expressions of SLC19A1, CYC1, RRM2B, and OCRL were clearly elevated in breast cancer, while RPS14 expression was considerably decreased." (PMID 35574387, 2022). "By performing the LASSO Cox regression analysis with 9 candidate genes in breast cancer patients of TCGA-BRCA training dataset, 5 pivotal genes were unearthed to establish the prognostic signature, Lactate Metabolism Index, namely LMI, including RPS14, SLC19A1, CYC1, RRM2B, OCRL." (PMID 35574387, 2022).
Down syndrome (4 papers, 2008 to 2024). "A common polymorphism (c.80A>G) in the gene coding for the reduced folate carrier (SLC19A1, commonly known as RFC-1) has been associated with maternal risk of the birth of a child with Down Syndrome (DS), but results are controversial." (PMID 23857226, 2013). "People with Down Syndrome have a third copy of SLC19A1, since it is on chromosome 21." (PMID 34200242, 2021). "Of note, a cluster of three genes involved in the transport of folate (SLC19A1), folate metabolism (FTCD), and homocysteine elimination (CBS) is located near the Down syndrome critical region on chromosome 21 (21q22.3)." (PMID 39062651, 2024). "Finally, a study on Down syndrome patients with and without CHD revealed that several variants in SLC19A1 are associated with the increased risk of AVSD, with odds ratios between 1.34 and 3.78, depending on the SNP and genetic model." (PMID 39062651, 2024).
leukemia (4 papers, 2014 to 2024). A malignant (clonal) hematologic disorder, involving hematopoietic stem cells and characterized by the presence of primitive or atypical myeloid or lymphoid cells in the bone marrow and the blood. "Transcriptional silencing, inactivating mutations and allele loss of SLC19A1 decreased the MTX influx in human leukemia cells." (PMID 29682186, 2018). "While increased folate metabolism in cancer cells is a well-reported phenomenon, and the use of antifolates was one of the earliest forms of leukemia chemotherapy, the role of SLC19A1 is largely unstudied in the context of tumor escape and invasion." (PMID 37575281, 2023). "Solute carrier family 19 member 1 (SLC19A1) transports reduced folate and is involved in methotrexate drug transportation in leukemia." (PMID 38534987, 2024). "A previous study reported that a murine leukemia cell line acquired PEM resistance by decreasing the expression of SLC19A1 and FPGS without an increase in the TYMS expression." (PMID 29682186, 2018).
neuroblastoma (4 papers, 2015 to 2025). Neuroblastoma (NB) is the most common solid, extracranial childhood tumor. "In high-risk neuroblastoma, SLC19A1 is upregulated by MYCN, enhances methotrexate uptake, and is associated with poor prognosis, indicating its potential as a therapeutic and prognostic target." (PMID 41376620, 2025). "Previous studies have demonstrated that SLC19A1 is associated with MYCN amplification in neuroblastoma and that SLC19A1 is a direct transcriptional target of N-myc." (PMID 32850011, 2020). "The high affinity of pralatrexate for the SLC19A1 encoded RFC-1 protein may demonstrate a potential role in the treatment of MYCN-amplified neuroblastoma." (PMID 32850011, 2020). "Additionally, the gene encoding the RFC-1 receptor, SLC19A1, is a direct transcriptional target of N-myc in neuroblastoma cells, suggesting a role for anti-folate drugs in the treatment of neuroblastoma." (PMID 32850011, 2020). "To determine whether N-Myc and its binding partner Max associate with E-box sites in the promoter region of the SLC19A1 gene in neuroblastoma cell lines, we employed chromatin immunoprecipitation (ChIP) assays." (PMID 25860940, 2015). "Finally, we investigated the association between SLC19A1 expression, established prognostic factors, and the risk of relapse and/or death in the cohort of 650 neuroblastoma patients." (PMID 25860940, 2015). "Furthermore, the correlations among CTLs, T-cell dysfunction, survival, and SLC19A1 expression were overviewed, revealing significant associations in neuroblastoma, acute myeloid leukemia (AML), metastatic melanoma, uterine corpus endometrial carcinoma, and triple-negative BRCA." (PMID 40149548, 2025). "Previous studies demonstrated that the expression of SLC19A1, the gene encoding the RFC-1 receptor, is associated with MYCN amplification in neuroblastoma." (PMID 32850011, 2020). "MYCN and SLC19A1 mRNA expressions were decreased with pralatrexate in MYCN-amplified neuroblastoma cells." (PMID 32850011, 2020). "High SLC19A1 expression therefore appears to be a common feature of poor-outcome neuroblastoma, particularly in tumors with MYCN amplification." (PMID 25860940, 2015). "Collectively, these results indicate that SLC19A1 is a direct transcriptional target of N-Myc in neuroblastoma cells." (PMID 25860940, 2015). "We subsequently investigated the expression of SLC19A1 in primary neuroblastoma tumors using a 42 sample discovery cohort and a 650 sample validation cohort." (PMID 25860940, 2015). "As previously discussed, SLC19A1 is down-stream target of N-myc in neuroblastoma." (PMID 32850011, 2020). "The findings presented in this study, although preliminary, provide new evidence to suggest that MYCN amplification leads to antifolate sensitivity, and that methotrexate may be beneficial in a subset of patients with MYCN-amplified neuroblastoma and high SLC19A1 expression." (PMID 25860940, 2015). "We found that down-regulation of SLC19A1 substantially decreases the rate of methotrexate uptake in neuroblastoma cells, indicating that RFC is also a major methotrexate uptake mechanism in neuroblastoma." (PMID 25860940, 2015). "The relationship between SLC19A1 and MYCN expression was examined in tumors from two independent patient cohorts, in a panel of 13 neuroblastoma cell lines and in cell lines with inducible and silenced MYCN expression." (PMID 25860940, 2015). "We have demonstrated that methotrexate uptake in neuroblastoma cells is mediated principally by the reduced folate carrier (RFC; SLC19A1), that SLC19A1 and MYCN expression are highly correlated in both patient tumors and cell lines, and that SLC19A1 is a direct transcriptional target of N-Myc." (PMID 25860940, 2015).
Arthritis (3 papers, 2012 to 2023). Inflammation of a joint. "The mRNA expressions of SLC19A1 in whole hind limbs and immune cells were examined 15 days after immunization (peak of arthritis)." (PMID 22546471, 2012). "SLC19A1 expression in immunized mice with arthritis was lower than in intact mice; moreover, SLC19A1 expression in arthritic mice was further decreased when they were treated with MTX." (PMID 22546471, 2012). "In the present study we examined the relationship between the efficacy of MTX and the expression of SLC19A1 in GPI-induced arthritis." (PMID 22546471, 2012). "We here examined the relationship between the efficacy of MTX and the expression of SLC19A1 in glucose 6-phosphate isomerase (GPI)-induced arthritis." (PMID 22546471, 2012). "We found that IL-6 regulated the expression of SLC19A1, so we also studied the effect of concomitant use of MTX and anti-IL-6 receptor (IL-6R) antibody in this arthritis model." (PMID 22546471, 2012). "In the present study, we demonstrated for the first time that the expression of the reduced folate transporter SLC19A1, which is important for MTX uptake into cells, is strongly related to the efficacy of MTX in an arthritis model." (PMID 22546471, 2012).
asthma (3 papers, 2009 to 2024). "For example, Strawberry Notch Homolog 2 (SBNO2) and Solute Carrier Family 19 Member 1 (SLC19A1) have been linked to asthma in previous GWA studies." (PMID 39108895, 2024). "Among the differentially co-expressed genes, eight were previously linked to asthma in genome- (MRPL14, ASB3, RHOBTB2) and epigenome-wide (CLC, EPS15, GPI, SSCRB4, STRN4) association studies and five were mentioned in the literature in the context of asthma (SLC19A1, MAEA, CLC, ATP1B1, and RECK)." (PMID 36835202, 2023).
folate deficiency (3 papers, 2014 to 2024). A nutritional condition produced by a deficiency of FOLIC ACID in the diet. "Several previous studies have shown that folate deficiency results in a significant upregulation of folate transport genes such as SLC19A1/RFC-1 and SLC46A1/PCFT." (PMID 30269276, 2018). "The SLC19A1 gene impacts folate transport into cells, leading to folate deficiency." (PMID 40822568, 2024).